MSX1 (msh homeobox 1)
Diseases named in the same sentence as MSX1 in open-access papers (continued):
Sharing a sentence is not in itself a finding about the gene and the disease.
melanoma (9 papers, 2019 to 2025). A malignant, usually aggressive tumor composed of atypical, neoplastic melanocytes. "MSX1 which has been shown to increase hepatic melanoma metastasis in an immune-deficient setting was only expressed in D4M melanoma and therefore could not account for the differences observed by us (data not shown)." (PMID 35109875, 2022). "Reactivation of neural crest-like transcriptional states has been observed in melanoma and other aggressive tumors, where factors such as MSH homeobox 1 (MSX1) and SRY-box transcription factor 10 (SOX10) drive dedifferentiation and enhance invasiveness." (PMID 41462674, 2025). "In contrast, the spindle type of melanoma is derived from fibroblasts, a less differentiated cell type with stronger MSX1 expression." (PMID 36012688, 2022). "Little is known about its role in melanocytes and melanoma, but there is evidence that MSX1 promotes melanoma progression and induces phenotype switching." (PMID 34071193, 2021). "The diverse roles of MITF, its upstream regulators, and MSX1 highlight that factors expressed during NC cell and melanocytic development contribute to melanoma cell plasticity." (PMID 34071193, 2021). "These cells express high levels of MSX1, indicating that this factor mediates dedifferentiation and probably plays a role in phenotype switching of melanoma cells." (PMID 34071193, 2021). "Epithelial cells in epithelioid melanomas are more differentiated cell types of ectodermal origin, and the downregulation of MSX1 and MSX2 expression in this type of tumor may indicate a lack of tumor suppression." (PMID 36012688, 2022). "In spindle and myxoid melanoma, on the other hand, MSX1 expression was high in tumor tissue." (PMID 36012688, 2022). "Interestingly, MSX1 expression levels correlate with disease progression in melanoma patients, and patients with high MSX1 expression levels have a poorer OS." (PMID 34071193, 2021). "Similarly, MSX1 expression is sufficient to reprogram melanoma cells as well by triggering a phenotype switch." (PMID 34071193, 2021). "In addition, we identified Mesenchyme (COL1A1+), Endothelium (SOX18+, KDR+), proliferating cells (TOP2A+, MKI67+), and some off‐target cells; Glial (MSX1+, SOX2+), Melanoma (PMEL+, PLP1+), and Neuron (DLL3, HES6)." (PMID 35322595, 2022). "MSX1 was also expressed in the retina and choroid of eyes with epithelioid and spindle-shaped melanomas but was not present in the retina or choroid of eyes with myxoid melanomas." (PMID 36012688, 2022). "Interestingly, the expression of MSX1 differed markedly between the different melanoma types-it was absent in epithelioid melanoma, higher in myxoid melanoma, and highest in spindle melanoma." (PMID 36012688, 2022).
Infertility (8 papers, 2012 to 2023). "MSX1 is critical for conferring uterine receptivity and readiness to implantation, it is significantly down-regulated in the receptive endometrium compared to the pre-receptive endometrium and reduced MSX1 in the endometrium is linked to infertility." (PMID 35197930, 2022). "Targeted mutation of Msx1 and Msx2 genes in female mice, which results in infertility, established that these factors suppress signaling by the morphogenic ligands, WNTS, in the uterus." (PMID 22383889, 2012). "In addition, the decrease in the MSX1 expression in human endometrial tissue is linked to infertility." (PMID 36835532, 2023). "The reduction of MSX1 in human endometrial tissue is linked to infertility." (PMID 36835532, 2023). "Interestingly, a decreased level of MSX1 in human and mouse endometrial tissue is linked to infertility, while SRXN1 contributes to oxidative stress resistance." (PMID 32232327, 2020). "Deletion of both Msx1 and Msx2 leads to complete infertility and aberrant expression of implantation-related genes." (PMID 31752681, 2019). "On the other hand, conditional ablation of both Msx1 and Msx2 in mouse uterus led to complete infertility due to a failure of embryo attachment to the uterine epithelium." (PMID 22383889, 2012). "Genetic studies in mice suggest that MSX1 is necessary for embryo implantation, and subsequent studies in humans revealed that the protein levels of MSX1, were significantly reduced in endometrial biopsies obtained of infertile women." (PMID 32244282, 2020). "A lack of Msx-1 in the murine uterus can lead to infertility due to impairment in the implantation window." (PMID 35308329, 2022).
colorectal cancer (6 papers, 2013 to 2025). A primary or metastatic malignant neoplasm that affects the colon or rectum. "MSX1 was a biomarker for the prognosis of colorectal cancer and a transcription factor involved in neural crest development that synergistically promotes astrocyte differentiation with other family members." (PMID 38383423, 2024). "In human tumor specimens, MSX1 displayed significantly increased expression in colonic neoplasia with a descending tendency during the lesion progression towards colorectal carcinoma." (PMID 30733598, 2019). "To identify the molecular mechanism underlying the ETV4-mediated EMT and metastasis in colorectal cancer cells, we next leveraged our RNA-seq data and a series of key downstream genes associated with EMT were further confirmed, including MER3, MSX1, LOXL2, THRB, WISP2, COL11A1, ADRB2 and E2F2." (PMID 41281746, 2025).
ovarian carcinoma (6 papers, 2007 to 2023). A malignant neoplasm originating from the surface ovarian epithelium. "The hypomethylation of MSX1 leads to decreased MSX1 expression, which is associated with cisplatin resistance in ovarian cancer cell lines, while MSX1 overexpression sensitizes cells to cisplatin." (PMID 36984544, 2023). "MSX1 encodes a member of the muscle segment homeobox gene family and can influence EMT in ovarian cancer." (PMID 36984544, 2023). "We also saw that forced overexpression of Msx1 in 2774 ovarian cancer cells with downregulated Msx1 expression reduced the expression of endogenous VEGF mRNA and its protein compared with control vector expression cells (data not shown)." (PMID 32784646, 2020). "Overexpression of the MSX1 suppresses cell growth and cell cycle progression in human ovarian cancer cell line by regulating the expression of key cell cycle regulators." (PMID 17662127, 2007). "Hypomethylation of developmental genes MSX1 and TMEM88 correlated with platinum resistance in patients with ovarian cancer." (PMID 31608277, 2019). "Hypermethylation of genes like ASS1, MLH1, and MSX1, and WNT pathway-related genes including DVL1, NFATC3, and SFRP5 was related to poor outcome of ovarian cancer patients treated with platinum-based chemotherapy." (PMID 28641578, 2017). "Human 2774 ovarian cancer cells tagged with a green fluorescence protein (GFP) were injected intraperitoneally into nude mice (n = 20 for each group), and then either Ad-mock or Ad-Msx1 was injected intraperitoneally." (PMID 32784646, 2020). "In ovarian cancer cells, MSX1 performs inhibition of cyclin D1 (CCND1) in addition to other cyclins and cell cycle regulators, while, in primary mesenchymal and epithelial progenitor cell types, MSX1 activates CCND1." (PMID 31779217, 2019).
colon cancer (4 papers, 2014 to 2022). "Even though MSX1 hypermethylation and down-regulation are also reported in colon cancer, Horazna and colleagues point out that MSX1 is overexpressed in colon villous adenomas and takes a crucial role in tumor initiation due to APC loss." (PMID 35486660, 2022). "Finally, we examined the expression pattern of human MSX1 in a collection of colonic tumors." (PMID 30733598, 2019).
Hodgkins lymphoma (4 papers, 2018 to 2021). A heterogeneous group of malignant lymphoid neoplasms of B-cell origin characterized histologically by the presence of Hodgkin and Reed-Sternberg (HRS) cells in the vast majority of cases. "MSX1: Muscle segment homeobox gene 1 (MSX1) is aberrantly expressed in several types of leukemia and lymphoma, including T-ALL, Hodgkin lymphoma (HL) and mantle cell lymphoma." (PMID 33921702, 2021). "Here, we introduce the NKL-code in normal hematopoiesis and focus on deregulated NKL homeobox genes in B-cell lymphoma, including HLX, MSX1 and NKX2-2 in Hodgkin lymphoma; HLX, NKX2-1 and NKX6-3 in diffuse large B-cell lymphoma; and NKX2-3 in splenic marginal zone lymphoma." (PMID 31779217, 2019).
mantle cell lymphoma (4 papers, 2018 to 2021). Mantle cell lymphoma is a rare form of malignant non-Hodgkin lymphoma affecting B lymphocytes in the lymph nodes in a region called the ``mantle zone''. "Deregulated NKL homeobox genes have been described in B-cell malignancies as well including MSX1 in mantle cell lymphoma, NKX2-1 in DLBCL, and NKX2-3 in marginal zone B-cell lymphoma." (PMID 29581848, 2018). "Muscle segment homeobox gene 1 (MSX1) is aberrantly expressed in several types of leukemia and lymphoma, including ALCL, HL, HSTL, mantle cell lymphoma (MCL) and T-ALL." (PMID 34829904, 2021).
adenoma (3 papers, 2019 to 2023). A neoplasm arising from the epithelium. "Whereas adenomas with intact Msx1 displayed a “typical” tubular shape, the Msx1-deficient tumors were transformed to adenomas with villus-like morphology." (PMID 30733598, 2019). "Moreover, in the mouse small intestine, Msx1 loss caused morphological changes reminding conversion from tubular to villous-like adenomas." (PMID 30733598, 2019). "scRNA-seq analysis of the LApc and LApcL adenoma cells confirmed the increased expression of Msx1 and Lyz1 after Lef1 deletion." (PMID 34788095, 2021). "Nevertheless, the most robust upregulation of MSX1 mRNA was detected in adenomas with low-grade dysplasia." (PMID 30733598, 2019). "In comparison with the LApc adenomas, the Lyz1+ cells in the LApcL adenomas were associated with an increased number of proliferating adenoma cells and cells expressing the ectopic crypt marker Msx1, which is not expressed in WT intestine." (PMID 34788095, 2021). "Moreover, the Lyz1+ Paneth-like cells were much more frequent in the Msx1+ adenoma areas in the LApcL mice than in the LApc mice." (PMID 34788095, 2021). "At days 7 and 21, cells producing Msx1 were present in (micro)adenomas." (PMID 30733598, 2019). "In Apc+/Min mice, Msx1 was detected in the upper portions of the small intestinal adenomas or in the colonic aberrant crypt foci (ACF), but not in the crypts." (PMID 30733598, 2019). "However, we did not observe any correlation between the adenoma type and MSX1 expression." (PMID 30733598, 2019).
B-cell lymphoma (3 papers, 2018 to 2019). "Of note, NKL homeobox genes HLX, NKX2-1, NKX2-3, NKX6-3 and MSX1 are deregulated in B-cell lymphoma and show aberrant activity in T-ALL as well which might indicate similar oncogenic functions in both lineages of lymphoid malignancies." (PMID 29581848, 2018). "Some of these identified genes have been previously shown to be deregulated in subsets of particular B-cell lymphomas, including HLX in HL, MSX1 in MCL, NKX2-1 in DLBCL, and NKX2-3 in SMZL, MALT lymphoma and DLBCL." (PMID 30308041, 2018).
cervical cancer (3 papers, 2020 to 2026). A primary or metastatic malignant neoplasm involving the cervix. "Recent studies have shown that MSX1 inhibits the Notch signaling pathway, thereby inducing cell cycle arrest and apoptosis in cervical cancer cells." (PMID 41614948, 2026). "We found that MSX1 expression enhances the clonogenic and migratory capacities of cervical cancer cell lines." (PMID 42248834, 2026). "In conclusion, our findings suggest that MSX1 plays a crucial role in cancer-related signaling pathways and may have implications for the development of therapeutic approaches in cervical cancer." (PMID 42248834, 2026).
craniosynostosis (3 papers, 2021 to 2025). Craniosynostosis is defined as the premature fusion of one or more cranial sutures leading to secondary distortion of skull shape resulting in skull deformities with a variable presentation. "MSX2 and MSX1 are homeobox genes involved in craniofacial development, that have previously been associated with craniosynostosis." (PMID 36982425, 2023). "Computed tomography scans showed parietal foramina in the OsxCre;Stat3fl/fl mice and morphological deformities including a circular shape and craniosynostosis that were similar to the phenotype of the Msx1 and Dlx5 deletion mice." (PMID 34824272, 2021). "Although MSX2 was not identified as a DEG in this analysis, MSX1, whose potential role in craniosynostosis is not well-defined, was increased in lambdoid and sagittal craniosynostosis in the primary model and sagittal craniosynostosis in the male-stratified model." (PMID 36982425, 2023).
diffuse large B-cell lymphoma (3 papers, 2018 to 2019). "Thus for example, NKX2-1 is ectopically expressed in diffuse large B-cell lymphoma (DLBCL), and the hematopoietic NKL homeobox genes NKX2-3 and NKX6-3 are overexpressed while MSX1 is downregulated in particular B-cell lymphomas." (PMID 30680064, 2018).
ectodermal dysplasia (3 papers, 2009 to 2023). "MSX1 mutations associated with ectodermal dysplasia or orofacial clefting disorders map to conserved domains in a non-random fashion." (PMID 19154605, 2009).
gastric cancer (3 papers, 2016 to 2025). A primary or metastatic malignant neoplasm involving the stomach. "Integration analysis of SNPs and gene expression profile revealed that FOXL1 regulated the most important DEGs of IRX1, SOX1, and MSX1 with risk associated SNP loci, which may serve as candidate biomarkers for diagnosis and prognosis of gastric cancer." (PMID 27403158, 2016).
hypospadias (3 papers, 2021 to 2025). Hypospadias is the displacement of the urethral meatus on the ventrum of the penis. "In WHS, hypospadias has been related to Muscle Segment Homeobox 1 (MSX1) deletion or haploinsufficiency." (PMID 41225980, 2025). "Based on the MSX1 gene function, its absence might be indirectly responsible for the hypospadias phenotype by contributing to the spatiotemporal regulation of GnRH transcription during development." (PMID 33627176, 2021). "Taken into account the deleted region of the second patient in the present report, it is possible that an haploinsufficiency of the MSX1 gene could explain the hypospadias phenotype." (PMID 33627176, 2021). "The 4p16.3 deletion presumably results in haploinsufficiency of the MSX1 gene [OMIM#142983] whose absence might be indirectly responsible for the hypospadias phenotype as this gene contributes to the spatiotemporal regulation of GnRH transcription during development." (PMID 36631813, 2023).
intestinal tumors (3 papers, 2019 to 2024). "Interestingly, similar to the expression of the Msx1 gene, which is also activated in intestinal tumors after Apc loss, the expression of the Trop2 gene is not uniform in tumors, but its production is restricted to specific tumor cells." (PMID 36077674, 2022). "In addition, co-deletion of Msx1 and Apc in ISCs of Msx1cKO/cKOApccKO/cKOLgr5-EGFP-IRES-CreERT2 mice altered the appearance of intestinal tumors." (PMID 30733598, 2019).
leukemia (3 papers, 2016 to 2021). A malignant (clonal) hematologic disorder, involving hematopoietic stem cells and characterized by the presence of primitive or atypical myeloid or lymphoid cells in the bone marrow and the blood. "Our data suggest synergistic inputs of AUTS2 and MEF2C in lymphopoiesis and leukemia (de)regulating NKL homeobox gene MSX1." (PMID 27322685, 2016). "Furthermore, a cryptic genomic alteration involving leukemia-related MSX1 gene was found in this case at the level of the array CGH." (PMID 29390452, 2017).
Nail dysplasia (3 papers, 2013 to 2024). The presence of developmental dysplasia of the nail. "Witkop syndrome, an uncommon autosomal dominant genetic disorder attributed to mutations in MSX1, held our attention due to its distinct dental and nail dysplasia characteristics." (PMID 38132417, 2023).
neuroblastoma (3 papers, 2009 to 2021). Neuroblastoma (NB) is the most common solid, extracranial childhood tumor. "Consistently with the convergence of Wnt and BMP signaling on MSX proteins, GSEA analysis confirmed a profound effect of Wnt3a/Rspo2 on the MSX1-regulated neuroblastoma transcriptome." (PMID 32210188, 2020). "As MSX1 has been shown to upregulate Notch signaling, we next examined the links between Wnt, BMP4, MSX1 and Notch in neuroblastoma." (PMID 32210188, 2020). "Here we identified MSX2 mediated activation of the NOTCH3-pathway in T-cells reminiscent of MSX1 in neuroblastoma." (PMID 19835636, 2009). "These include EPAS1 and MSX1, both of which have been shown to inhibit neuroblastoma cell growth." (PMID 32210188, 2020). "MSX1 is already known to be downstream of BMP signaling in the developing neural crest and has been shown to suppress proliferation and colony formation in soft agar when exogenously over-expressed in neuroblastoma cells." (PMID 32210188, 2020).
acute lymphoblastic leukemia (2 papers, 2017). Leukemia with an acute onset, characterized by the presence of lymphoblasts in the bone marrow and the peripheral blood. "While T-cell acute lymphoblastic leukemia (T-ALL) subsets exhibit aberrant overexpression of MSX1, we show here that in malignant NK-cells the level of MSX1 transcripts is aberrantly downregulated." (PMID 28977998, 2017). "T-cell acute lymphoblastic leukemia (T-ALL) cells represent developmentally arrested T-cell progenitors, subsets of which aberrantly express homeobox genes of the NKL subclass, including TLX1, TLX3, NKX2-1, NKX2-5, NKX3-1 and MSX1." (PMID 28151996, 2017).
atrial septal defect (2 papers, 2019 to 2025). Interauricular communication is a congenital malformation characterized by a communication between the atrial chambers of the heart. "In the atrial septum, we identified a distinct endocardial cushion-related population marked by strong LEF1 and MSX1 expression, supporting a potential causal role for these transcription factors in atrial septal defects." (PMID 41162788, 2025). "A locus in chromosome 4p16, adjacent to MSX1 and STX18, has been associated with atrial septal defects (ASD) in multiple European and Chinese cohorts." (PMID 31712678, 2019).